GLUL (glutamate-ammonia ligase)
Diseases named in the same sentence as GLUL in open-access papers (continued):
Sharing a sentence is not in itself a finding about the gene and the disease.
cancer (continued). "Furthermore, the knockdown of GLUL was found to promote cancer cell growth and invasive metastasis in vitro and in vivo." (PMID 40598593, 2025). "Previous literature has discussed the potential of GLUL inhibitors as cancer treatment drugs." (PMID 39519347, 2024). "However, explanations as to how GLUL regulates the immune microenvironment and cancer development through the inflammatory pathways are largely lacking." (PMID 36619229, 2023). "Since other pathways may also be involved in tamoxifen resistance, therfore we analyzed the interaction between miRNA-targeting genes and upregulated mRNAs and discovered GLUL plays an important role in cancer progression." (PMID 36619229, 2023). "Similarly, NAA levels in ascitic fluid also augmented with the cancer stage and it correlated with GLUL levels in TAMs." (PMID 34260142, 2021). "In addition, thymosin-β4 (TMSB4X) and glutamate-ammonia ligase (GLUL), which were significantly upregulated by HBV genotype C and A infections, respectively, have been reported to be associated with other cancers." (PMID 34696350, 2021). "Furthermore, a recent study reported that GLUL overexpression sensitized NSCLCs to anti-cancer drug gefitinib treatment." (PMID 31817360, 2019). "Interestingly, GLUL KO/KD resulted in a gain of function phenotype with induced drug resistance in specific cancer cell types, including the non-small cell lung cancer (NSCLC) cell line A549." (PMID 31817360, 2019). "In addition, the expression of GLUL in luminal type cancers correlates with the ability to synthesize glutamine from ammonia and glutamate, and therefore describes at the molecular level a type of cancer that is predicted to be more resistant to glutamine deprivation treatment." (PMID 21852960, 2011). "The key glutamine-synthesizing enzyme, glutamate-ammonia ligase (GLUL), is upregulated in most human cancers and in M2-like macrophages." (PMID 38701369, 2024). "The siRNA oligos for GLUL, ALDH2, BLVRA or FBP1 were introduced into cancer tissue derived CA-13 cells." (PMID 38580938, 2024). "This phosphorylation event leads to the subsequent phosphorylation of GLUL, which contributes to increased lysosome membrane permeabilization (LMP), a common phenomenon in cancer cells." (PMID 38149248, 2023). "In some types of human and mouse cancers, MYC induces the overexpression of glutamate ammonia ligase (GLUL), also called GS, which is responsible for de novo GLN synthesis." (PMID 34503536, 2021). "We investigated the effect of reduced GLUL expression using siRNA or lentiviral CRISPR-Cas9 mediated knockout (KO), as well as doxycycline-inducible shRNA-mediated knockdown (KD) in different cancer cell lines." (PMID 31817360, 2019). "Furthermore, re-expression of GLUL in KO cells restored the sensitivity of cells to drug treatment, suggesting that the expression level of GLUL might influence drug sensitivity in specific cancer cell types." (PMID 31817360, 2019). "The nine mRNAs are coding for proteins involved in cell cycle regulation (CDCA7L), modification of the T cell and B cell immune response (GBP2, GLUL, HERC5, PPP3CC), erythropoiesis (GBP2), and cell migration of cancer and hematopoietic cells (HERC5, HMHA1)." (PMID 28236054, 2017). "Intriguingly, GLUL-knockdown MCF-7 cells became more cuboidal shape in comparison with shLuciferase control cells, which is the typical morphology of epithelial-like luminal cancer." (PMID 36619229, 2023). "Previous studies have identified that GLUL as an enzyme plays a fundamental role in obtaining the prometastatic function of TAM and there is a crosstalk mechanism whereby cancer cells released N‐acetylaspartate to enhance GLUL expression in TAM and further prompt M2‐like phenotypes of TAM." (PMID 36587392, 2023). "The combination of GLUL and SQSTM1 inhibitors in precisely characterized patients may have superior effects against cancer compared to immunotherapy alone." (PMID 38149248, 2023).
cancer (continued). "Moreover, the high level of glutamine synthetase (GLUL) was positively correlated with the expression of HER-2 and proliferation of cancer cell." (PMID 33173435, 2020). "Here, we reported that GLUL ablation conferred resistance to several anticancer drugs in specific cancer cell lines while leaving other cell lines non-resistant to the same drugs." (PMID 31817360, 2019). "While there is an apparent net consumption of glutamine in most cancer types, glutamine can also be synthesized from glutamate and ammonia by glutamine synthetase (coded for by the GLUL gene), a process that is also important in cancer under some circumstances." (PMID 31096630, 2019). "Additionally, lactate treatment increased the expression of ASCT2 and GLS1, but not GLUL, in cancer cells." (PMID 39690134, 2024). "Thus, even in the absence of chemotherapeutic drugs, GLUL KO cancer cells should be more dependent on the support of this shuttle for mitochondrial NADH production and more sensitive to its inhibition." (PMID 31817360, 2019). "In addition, glutamate–ammonia ligase (GLUL) is not overexpressed in any type of cancer under study, hence indicating that glutamine is not synthesized from glutamate in cancer in general." (PMID 29116024, 2017).
infection (20 papers, 2010 to 2026). The state of being infected such as from the introduction of a foreign agent such as serum, vaccine, antigenic substance or organism. "Furthermore, gene expression of glycolytic enzymes, lactate, and glutamine metabolism (G6PDH, PKLR, PFKL, LDHA, LDHB, GLS1, GLS2, and GLUL), were upregulated in primary mouse (hACE2) and human hepatocytes upon infection compared to controls." (PMID 35978143, 2022). "GLUL expression in the livers with HBV genotype C infection is not upregulated compared with that in the livers with HBV genotype A infection, suggesting an association between GLUL expression with the difference in HCC incidence among HBV genotypes." (PMID 34696350, 2021).
cardiovascular disease (2 papers, 2018 to 2023). "In addition, mutations in the glutamate ammonia ligase (GLUL) gene and high glutamate levels increase the risk of cardiovascular disease." (PMID 37958896, 2023).
GLUL also shares sentences with these, for which no sentence is quoted: type 1 diabetes (13 papers); hepatocellular adenoma (9); temporal lobe epilepsy (9); Cirrhosis (7); stiff-person syndrome (7); ischemia (6); multiple myeloma (5); cerebellar ataxia (4); Hyperglycaemia (4); metastatic disease (4); neurological disorders (4); psychiatric disorder (4); acute liver failure (3); adenoma (3); Anxiety (3); autism (3); brain disorder (3); colorectal cancer (3); Epileptic encephalopathy (3); hypothyroidism (3); oligodendroglioma (3); status epilepticus (3); autoimmune encephalitis (2); bipolar disorder (2); cholangiocarcinoma (2); COVID-19 (2); diabetic retinopathy (2); epileptic seizures (2); Familial adenomatous polyposis (2); fibrosarcoma (2).
A further 92 diseases each share a sentence with GLUL in 2 papers or fewer.